BMI1 (BMI1 proto-oncogene, polycomb ring finger)
Diseases named in the same sentence as BMI1 in open-access papers (continued):
Sharing a sentence is not in itself a finding about the gene and the disease.
medulloblastoma (30 papers, 2009 to 2026). A malignant, invasive embryonal neoplasm arising from the cerebellum. "Here we show that loss of TWIST1 resulted in reduced BMI1 expression and inhibition of Group 3 medulloblastoma metastasis." (PMID 30297829, 2018). "High level of BMI1 is associated with medulloblastoma invasion and is also considered to be a poor prognostic marker in multiple human cancers, and is significantly involved in chemoresistance and tumor recurrence." (PMID 25526772, 2014). "We now show that in medulloblastoma cells decreased β1-subunit levels are associated with increased proliferation and tumorigenesis and suggest that at least in part Bmi1 mediates its effects on tumor progression through repression of the β1-subunit of Na,K-ATPase." (PMID 26286140, 2015). "The protein BMI1, a known regulator of stem cell renewal and tumorigenesis, is overexpressed in medulloblastoma and supports tumor growth." (PMID 41514664, 2026). "The study used the PD325901, a MEK inhibitor that blocks ERK phosphorylation, as the MAPK/ERK pathway inhibitor in combination with BMI1 inhibition to evaluate synergistic effects on medulloblastoma cells." (PMID 41514664, 2026). "Here, we identify a BMI1-dependent sensitivity to deregulation of inositol metabolism in a proportion of medulloblastoma." (PMID 33846320, 2021). "Of note, similarly to NOTCH1, BMI1 and Nestin are weakly expressed in Group 3 medulloblastoma primary tumors from D425 xenografted mice." (PMID 30297829, 2018). "Here, the authors show that in Group 3 medulloblastoma NOTCH1 activates BMI1 through the activation of TWIST1, driving metastasis and self-renewal, and in mouse models a NOTCH1 blocking antibody decreased spinal metastases." (PMID 30297829, 2018). "TWIST1-silenced medulloblastoma cells present reduced BMI1 expression, while BMI1-silenced medulloblastoma cells present similar levels of TWIST1 expression as compared with control." (PMID 30297829, 2018). "Our findings suggest that NOTCH1-induced medulloblastoma metastasis occurs through TWIST1-induced BMI1 activation." (PMID 30297829, 2018). "Together, these findings indicate that the NOTCH1-induced TWIST1 activation contributes to the activation of BMI1, therefore inducing Group 3 medulloblastoma metastasis." (PMID 30297829, 2018). "In medulloblastoma, SHH/Gli has been shown to drive expression of stem cell modulator Bmi1, a key transcriptional polycomb repressor, found to be overexpressed in medulloblastoma and in CD133+ tumor initiating progenitors." (PMID 27043632, 2016). "Recent studies showed that Bmi1 is aberrantly expressed in medulloblastoma which correlates with the activation of the Shh pathway and is required for Shh driven medulloblastoma expansion." (PMID 26286140, 2015). "We now found an inverse relationship between Bmi1 and β1-subunit levels in CGP cells and Smo/Smo medulloblastoma and that Bmi1 suppressed the promoter activity of the β1-subunit identifying Bmi1 as a novel transcriptional regulator of the β1-subunit." (PMID 26286140, 2015).
medulloblastoma (continued). "One of the target genes of Gli1 is the polycomb protein Bmi1, a transcriptional suppressor that is upregulated upon Shh activation in medulloblastoma." (PMID 26286140, 2015). "It has previously been shown that activation of Shh or overexpression of Gli1 induced Bmi1 expression and knockdown of Bmi1 reduced medulloblastoma growth." (PMID 26286140, 2015). "Over-expression of BMI1 has been reported in many different human cancers, including medulloblastoma and adult GBM." (PMID 25526772, 2014). "Here we demonstrate that human medulloblastoma of Group 4 characterised by the greatest overexpression of BMI1, also display deregulation of cell adhesion molecules." (PMID 24460684, 2014). "BMI1 is a Polycomb group repressor complex gene overexpressed across medulloblastoma subgroups but most significantly in Group 4 tumours." (PMID 24460684, 2014). "miR-128a increases intracellular ROS levels by targeting Bmi1, resulting in inhibition of cancer cell growth in medulloblastoma cells." (PMID 24312366, 2013). "Addition of transgenic expression of Bmi1 transgene resulted in a similar amount and penetrance of medulloblastomas (GCre;p53Lox/Lox;RbLox/Lox; Bmi1LSL, n = 4)." (PMID 22574128, 2012). "Recent studies have documented increased BMI1 expression in a variety of human cancers, such as non-small cell lung cancers, medulloblastomas, prostate carcinomas, colorectal cancers, breast carcinomas, and oesophageal squamous cell carcinomas (ESCCs)." (PMID 23046527, 2012). "Regulation of Bmi-1 by microRNAs is exciting given that Bmi-1 is over-expressed in medulloblastoma and critical for normal cerebellar development." (PMID 20574517, 2010). "We found that miR-128a inhibits growth of medulloblastoma cells by targeting the Bmi-1 oncogene and thereby increasing the steady-state levels of superoxide and promoting cellular senescence." (PMID 20574517, 2010). "Medulloblastoma cells were transfected with miR-128a, miR-128a and Bmi-1 or the corresponding controls and the cells subjected to the colony focus assay." (PMID 20574517, 2010). "Restoring Bmi-1 expression in miR-128a expressing cells rescues the medulloblastoma cells from growth arrest." (PMID 20574517, 2010). "We demonstrate that miR-128a has growth suppressive activity in medulloblastoma and that this activity is partially mediated by targeting Bmi-1." (PMID 20574517, 2010). "The polycomb group gene Bmi1, which is required for neural stem cell self-renewal and also controls anti-oxidant defense in neurons, is upregulated in several cancers, including medulloblastoma." (PMID 19823589, 2009). "Taken together, our results support the idea that silencing of EPHA7 in human follicular lymphoma and medulloblastoma might occur upon BMI1 overexpression." (PMID 27533460, 2016). "Downregulation of the β1-subunit could be mimicked by expressing the transcription factors Gli1, a well-known member of the Shh signaling cascade, and Bmi1, a polycomb protein that can be induced by Shh/Gli1 in medulloblastoma." (PMID 26286140, 2015). "Bmi1 is necessary for the progression of Shh induced medulloblastoma." (PMID 22574128, 2012). "Transgenic expression of Bmi1 failed to generate medulloblastoma even in the presence of the predisposing deletion of Rb." (PMID 22574128, 2012). "One of these, miR-128a, inhibits growth of medulloblastoma cells by targeting the Bmi-1 oncogene." (PMID 20574517, 2010). "We then sought to further explore the mechanism of the miR-128a-Bmi-1 pathway in medulloblastoma." (PMID 20574517, 2010). "Additionally, Bmi1 could be a critical downstream target of hedgehog pathway and participate in the hedgehog pathway to modulate self-renewal of medulloblastoma brain tumor-initiating cells." (PMID 31171917, 2019). "Furthermore, Bmi1 was found to control medulloblastoma cell invasion, cell adhesion and motility." (PMID 26286140, 2015).
medulloblastoma (continued). "Hence, aberrant BMI1 expression might also be involved in the characteristics of the ‘more aggressive’ cancer cell population after CRT, because BMI1 is thought to be a downstream target in the Hh pathway in medulloblastoma." (PMID 23046527, 2012). "To further evaluate whether Bmi-1 repression is a functional component of the miR-128a growth arrest phenotype we investigated whether Bmi-1 could rescue the miR-128a growth arrest in medulloblastoma cells." (PMID 20574517, 2010). "PTC-028, a specific inhibitor of BMI1, inhibits CSC self-renewal of medulloblastoma in vitro, reduces tumor burden in both local and metastatic compartments, and suppresses the tumor initiation ability of recurrent medulloblastoma in vivo." (PMID 33499351, 2021). "On the other hand, both TWIST1- and BMI1-silenced medulloblastoma cells present similar levels of NICD1 expression as compared with control, suggesting that NOTCH1 is upstream of TWIST1 and BMI1." (PMID 30297829, 2018). "Multiple other genes belonging to PRC1 and PRC2 complexes, including BMI1, EED and SUZ12 have been found upregulated either in specific medulloblastoma subgroups or across medulloblastoma generally." (PMID 29759978, 2018). "find convergence of the chromatin modifiers BMI1 and CHD7 in medulloblastoma pathogenesis, and they show that this pathway regulates tumor proliferation and growth via ERK signaling." (PMID 29212025, 2017). "Another medulloblastoma cell line ONS76 cells also showed the same trend in plating efficiency when transfected with miR-128a and Bmi-1." (PMID 20574517, 2010). "A study investigates whether targeting BMI1, alone or in combination with MAPK/ERK pathway inhibitors, could be an effective treatment strategy against medulloblastoma." (PMID 41514664, 2026). "BMI1 and CHD7 are chromatin remodelling genes with a role in medulloblastoma pathogenesis." (PMID 33846320, 2021). "We describe molecular convergence between BMI1 and CHD7 in the initiation of medulloblastoma." (PMID 29212025, 2017). "Analysis of two publicly available datasets, GSE3526 and GSE37418, revealed that compared to normal cerebellum, human medulloblastoma tumors showed decreased ATP1B1 and increased Bmi1 levels across all subgroups with a p-value of 4.1e-07 (ATP1B1) and 9.2e-28 (Bmi1)." (PMID 26286140, 2015). "While Bmi1 overexpression has been suggested as a mechanism in the pathogenesis of medulloblastoma, Bmi1 overexpression itself did not induce medulloblastoma but rather appeared to enhance tumor cell survival and proliferation." (PMID 26286140, 2015). "From this breeding we did not observe medulloblastoma upon transgenic over expression of Bmi1 and instead virtually all tumors observed in the GFAP-Cre;Bmi1LSL; RbLox/Lox mice were pituitary tumors." (PMID 22574128, 2012). "In addition, Manoranjan proposed that the inhibition of self-renewal pathways such as Bmi1 and Sox2 could explain the improved outcome in WNT medulloblastoma." (PMID 34577571, 2021). "Ectopic Wnt activation in primary patient-derived medulloblastoma lines proved that the activation of the Wnt/β-catenin pathway in WNT3A-conditioned medium significantly reduced the self-renewal capacity along with the Sox2 and Bmi1 expression in Group 3 and Group 4 medulloblastoma lines." (PMID 34577571, 2021). "The target genes of Bmi1 in medulloblastoma are not well-known." (PMID 26286140, 2015). "A lesser expression of both Bmi1 and Sox2 is observed in WNT medulloblastoma BTICs compared to non-WNT cells." (PMID 34577571, 2021).
acute myeloid leukemia (26 papers, 2011 to 2025). Acute myeloid leukemia (AML) is a group of neoplasms arising from precursor cells committed to the myeloid cell-line differentiation. "Interference of EZH2 function by the small-molecule histone methyltransferases inhibitor, DZNep, is reported to increase ROS levels in acute myeloid leukemia cells like in Bmi1-deficient mice." (PMID 22606246, 2012). "A study of hematologic malignancies reported that BMI1 was highly expressed in patients with acute myelogenous leukemia or chronic myelogenous leukemia compared to the normal control group." (PMID 34442383, 2021). "In particular, high levels of BMI1, an oncogene highly expressed in acute myeloid leukemia and in advanced phases of CML, were connected to a poorer outcome, whereas on the other side a high expression of CBX6 and CBX7 played a favorable role." (PMID 30574454, 2018). "In acute myeloid leukemia, BMI1 is over-expressed, while other genes from the same family, such as CBX6 and CBX7, are down-regulated." (PMID 30574454, 2018). "In this regard, BMI1 is overexpressed and promotes cancer cell self-renewal in acute myeloid leukemia and several solid tumor types, such as pancreatic cancer, glioblastoma multiforme, diffuse intrinsic pontine glioma, colorectal cancer, and epithelial ovarian cancer." (PMID 30781493, 2019). "Knowing that Bmi1 expression is essential for maintenance of leukemic stem cells, we speculate that Twist1 might govern the pathogenesis of acute myeloid leukemia (AML) development as well." (PMID 26832848, 2015). "BMI1 exhibits elevated expression levels and facilitates the self-renewal capacity of cancer cells in acute myeloid leukemia (AML) and various solid tumor malignancies." (PMID 40675967, 2025). "BMI1 gene expression levels correlate well with progression and prognosis of myelodysplastic syndrome (MDS) and acute myeloid leukemia (AML)." (PMID 33540760, 2021). "The expression of BMI1/PCGF4 has correlated with disease progression and the prognosis of myelodysplastic syndrome (MDS), the prognoses of acute myeloid leukemia (AML) and chronic myeloid leukemia." (PMID 33374737, 2020). "In acute myeloid leukemia cell lines, PTC-596 decreases BMI1 and H2AK119ub1 levels and induces apoptosis, while it also prolongs survival in xenograft mouse models of acute myeloid leukemia." (PMID 30781493, 2019). "BMI1 is upregulated in multiple tumors including lymphomas prostate, breast, colon, and non-small cell lung cancer (NSCLC), as well as in hematological malignancies such as acute myeloid leukemia (AML) and myelodysplastic syndrome (MDS)." (PMID 31380371, 2019). "On the other hand, as expected, BMI1 was also detected in other myeloid and lymphoid tumors (essential thrombocytemia, acute myeloid leukemia, follicular lymphoma), but in all these cases it was never co-expressed with CD26 nor, obviously, with P210." (PMID 30574454, 2018). "Interestingly, high expression of BMI1, RING1A, and/or RING1B correlates with worse overall survival in acute myeloid leukemia, suggesting that high H2AK119ub1 levels may be pathogenic." (PMID 30781493, 2019). "It has also been reported that the basal Bmi-1 levels may not be a determinant of PTC-209 sensitivity at least in acute myeloid leukemia." (PMID 31695609, 2019). "PTC-596 is another commonly used small molecule BMI1 inhibitor that can selectively induce massive death of acute myeloid leukemia (AML) stem/progenitor cells without affecting normal hematopoietic cells." (PMID 38515119, 2024). "Further, in transgenic mice that constitutively overexpress human SALL4B, there is up-regulated expression of BMI-1, and the levels of BMI-1 in these mice increase as they progress from normal to preleukemic (myelodysplastic syndrome [MDS]) and leukemic (acute myeloid leukemia [AML]) stages." (PMID 29308206, 2018).
cervical carcinoma (25 papers, 2009 to 2025). A carcinoma arising from either the exocervical squamous epithelium or the endocervical glandular epithelium. "High expression of BMI1 is significantly associated with poor tumor differentiation, high clinical grade, and poor prognosis of cervical cancer, and is an independent prognostic factor in cervical carcinoma." (PMID 33927214, 2021). "So far, overexpression of Bmi-1 has been reported in association with human carcinomas such as hematologic cancer, pancreatic cancer, cervical cancer, laryngeal squamous cell carcinoma, and gastric cancer." (PMID 32059385, 2020). "The results showed that the proto-oncogene Bmi-1 was associated with clinical stage, tumor grade and lymphatic metastasis, and the Hk6 gene was overexpressed in cervical cancer." (PMID 31744495, 2019). "Finally, expression of the stem cell self-renewal-associated transcription factors OCT4, NANOG, KLF4 and BMI1 is elevated in ALDHhigh cervical cancer cells." (PMID 24318570, 2013). "BMI1 has been reported to be upregulated in cervical cancer and promoted cancer progression and tumorigenesis." (PMID 39793896, 2025). "To date, few studies have reported the deregulation of components of PRC1 and their role in cervical cancer, with the exception of BMI1." (PMID 39793896, 2025). "It showed that BMI1 gene plays an important role in cervical cancer progression and closely correlates with autophagy of cervical cancer cells." (PMID 33927214, 2021). "Immunohistochemical results of tumor tissues also verified the inhibitory effects of AL on BMI1 in cervical cancer tissues, and its regulating effects on EMT and autophagy." (PMID 33927214, 2021). "Enhanced expression of multiple ‘stemness’ genes (Bmi1, Nanog and Oct-4) was detected in spheroid cells as compared with attached cells, which indicated that primary cervical cancer tissue harboured a population of CSCs." (PMID 32507856, 2020). "The functional target of miR-376c-3p is the BMI1 polycomb ring finger proto-oncogene which is highly expressed in several cancer types, including cervical cancer." (PMID 32154165, 2020). "Our analysis of primary human cervical carcinomas indicates that BMI1 expression is significantly reduced in HPV+ tumors with respect to HPV- tumors." (PMID 29069809, 2017). "In the current study, the expression level of Bmi-1, p16, and CD44v6 proteins in cervical cancer was detected using immunohistochemical staining." (PMID 23691455, 2012). "The findings of the present study demonstrated that Bmi-1 protein expression had a tendency of up-regulation in normal cervical mucosa, cervical carcinoma, and UCC." (PMID 23691455, 2012). "The expression of Bmi-1, p16, and CD44v6 was significantly high in cervical carcinoma compared with that in the cervical neoplasia and normal colorectal mucosa (P<0.05)." (PMID 23691455, 2012). "In this study,BMI-1 proteins were isolated by screening of a T7 phage cDNA library from mixed cervical carcinoma tissues." (PMID 22132147, 2011). "We analyzed the expression of BMI-1 in several human cervical carcinoma cell lines using RT-PCR or Western blot." (PMID 22132147, 2011). "Using ELISA and immunodetection approaches, we demonstrate for the first time that BMI-1 mRNA was over-expressed at different levels in cervical carcinoma cell lines." (PMID 22132147, 2011). "We further analyzed our results using logistic regression and ROC curve, which showed that the BMI-1 autoantibody as potential biomarker for cervical carcinoma has similar sensitivity and specificity to BMI-1." (PMID 22132147, 2011). "We analyzed BMI-1 autoantibody levels in serum samples from 67 patients with cervical carcinoma and 65 controls using ELISA and immunoblot." (PMID 22132147, 2011). "The ratio of BMI-1 expression in cervical carcinoma cell lines was singnificantly increased in all of the three cervical carcinoma cell lines compare to that in H8 cell line (P<0.05)." (PMID 22132147, 2011).